Y_RNA (Y RNA )
Gene: Miscellaneous RNA gene on chromosome X (134,142,228 to 134,142,340, reverse strand). Ensembl gene ENSG00000200572.
Homologues: Orthologues: macaque Y_RNA (96% identical), chimpanzee Y_RNA (90% identical). Paralogues in human: RNY1 (85% identical), RNY1P11 (84% identical), Y_RNA (84% identical), Y_RNA (83% identical), RNY1P8 (82% identical), Y_RNA (82% identical), Y_RNA (81% identical), RNY1P10 (81% identical), RNY1P12 (81% identical), Y_RNA (80% identical), Y_RNA (79% identical), Y_RNA (78% identical), and 94 more.